ANKIB1 (ankyrin repeat and IBR domain containing 1)
Description:
Might act as an E3 ubiquitin-protein ligase, or as part of E3 complex, which accepts ubiquitin from specific E2 ubiquitin-conjugating enzymes and then transfers it to substrates.
Synonyms: KIAA1386; DKFZP434A0225
Tractability: Antibody: the Human Protein Atlas places it where antibodies can reach. PROTAC: ubiquitination databases record sites on it; its protein half-life has been measured.
Gene: Protein-coding gene on chromosome 7 (92,245,973 to 92,402,070, forward strand). Ensembl gene ENSG00000001629.
Subcellular location (Human Protein Atlas): Cytosol; Plasma membrane
Gene Ontology:
Molecular function: protein binding; ubiquitin conjugating enzyme binding; ubiquitin protein ligase activity; ubiquitin-protein transferase activity; zinc ion binding
Biological process: protein ubiquitination
Cellular component: cytosol; plasma membrane; ubiquitin ligase complex
Genetic constraint (gnomAD): Loss-of-function variants: 38 observed, 93.48 expected, observed/expected ratio (o/e) 0.41, 90% interval 0.31 to 0.53. The upper end of that interval is the gene's LOEUF score, 0.53, which puts it in group 2 of 6, group 1 being the genes least tolerant of losing a copy. Missense variants: 882 observed, 1,189.3 expected, observed/expected ratio (o/e) 0.74, 90% interval 0.7 to 0.78. Synonymous variants: 357 observed, 407.06 expected, observed/expected ratio (o/e) 0.88, 90% interval 0.8 to 0.96.
Homologues: Orthologues: chimpanzee ANKIB1 (99% identical), macaque ANKIB1 (99% identical), dog ANKIB1 (97% identical), pig ANKIB1 (95% identical), rat Ankib1 (94% identical), guinea pig ANKIB1 (94% identical), mouse Ankib1 (93% identical), rabbit ANKIB1 (93% identical), tropical clawed frog ankib1 (81% identical), zebrafish ankib1b (74% identical), Caenorhabditis elegans C17H11.6 (11% identical), Caenorhabditis elegans Y49F6B.9 (8% identical). Paralogues in human: ARIH1 (14% identical), ARIH2 (14% identical), RNF19A (14% identical), RNF19B (11% identical), RNF14 (9% identical), RNF217 (8% identical), PRKN (8% identical), RNF144A (7% identical), RNF144B (6% identical).
Diseases named in the same sentence as ANKIB1 in open-access papers:
ANKIB1 is named in the same sentence as 4 diseases in open-access papers, as found by Europe PMC text mining. Sharing a sentence is not in itself a finding about the gene and the disease. The quoted sentences say what the papers report.
autism spectrum disorder (1 paper, 2023). A spectrum of developmental disorders that includes autism, and Asperger syndrome. "ANKIB1 (rs2040498) is a protein‐coding gene predicted to be involved in ubiquitin‐associated activity and has been identified in angiokeratoma corporis diffusum with arteriovenous fistulas and autism spectrum disorder (L.‐S." (PMID 37337823, 2023).
tumor (2 papers, 2022 to 2025). "The list included the genes MAD1L1, HECW1, and ANKIB1, which have been reported to be involved in mitotic checkpoint control and have been previously implicated in tumor progression." (PMID 40722723, 2025). "While the silencing of circAnkib1 and circCsnk1g3 showed a profound effect on tumor growth in vivo, the silencing of linear Ankib1 and Csnk1g3 transcripts with shRNAs specific to the linear isoforms did not impact tumor growth." (PMID 36433954, 2022).
ANKIB1 also shares sentences with these, for which no sentence is quoted: bone cancer (1 paper); major depressive disorder (1).